TNF (tumor necrosis factor)
Diseases named in the same sentence as TNF in open-access papers (continued):
Sharing a sentence is not in itself a finding about the gene and the disease.
rheumatoid arthritis (continued). "For example, etanercept (an antagonist of TNF-α) was only effective in a subset of MG patients and aggravates MG symptoms in rheumatoid arthritis patients." (PMID 40597804, 2025). "In synovial inflammatory conditions such as rheumatoid arthritis, activated synovial macrophages and synovial fibroblasts secrete proinflammatory cytokines such as IL-1, IL-6, and TNF-α." (PMID 40128226, 2025). "TNF-α inhibitors are commonly used to treat numerous chronic autoimmune diseases such as rheumatoid arthritis, Crohn’s disease, systemic lupus erythematosus, ulcerative colitis, psoriasis and psoriatic arthropathy." (PMID 40371340, 2025). "Under inflammatory conditions in rheumatoid arthritis (RA), several molecules such as IL-1β, IL-6, TNF-α, IL-17, and hypoxia-inducible factor-1α (HIF-1α) are produced, which can mediate bone loss." (PMID 40153574, 2025). "In conclusion, TNF-α blockers are approved to treat a variety of diseases like rheumatoid arthritis, psoriasis, juvenile idiopathic arthritis, and inflammatory bowel disease (Crohn’s disease and ulcerative colitis)." (PMID 39114193, 2024). "It reduces pro-inflammatory cytokines, i.e., interleukin-6 (IL-6), and tumor necrosis factor-α (TNF-α) production in a rheumatoid arthritis rat model." (PMID 38390130, 2024). "IL-6 and TNF-α are well known to be involved in rheumatoid arthritis, with IL-6 promoting joint inflammation and destruction through cell signaling, and TNF-α initiating an inflammatory response leading to joint swelling and bone destruction." (PMID 39337919, 2024). "Tumor necrosis factor alpha (TNF-α) inhibitors are commonly used in the treatment of several autoimmune disorders such as rheumatoid arthritis, psoriasis, and Crohn’s disease." (PMID 38337403, 2024). "Biomarkers guide renal carcinoma treatments, while gene expression profiles predict rheumatoid arthritis outcomes with tumor necrosis factor-alpha (TNF-α) blockers." (PMID 39328627, 2024). "In patients with long-standing severe rheumatoid arthritis, TNF-α blockade had a beneficial effect on endothelial function." (PMID 39591217, 2024). "KEGG enrichment analysis post-LPS treatment in Landrace pigs highlighted inflammatory signaling pathways, including rheumatoid arthritis, cytokine–receptor interaction, IL-17, NF-κB, and TNF signaling pathways." (PMID 39765872, 2024). "Immunological diseases such as rheumatoid arthritis (RA), as described in this case, induce chronic inflammation mediated by cytokines (e.g., TNF-α, IL-6), degrading the extracellular matrix of the sclera and increasing susceptibility to trauma." (PMID 39949387, 2024). "Tumor necrosis factor α (TNF-α) inhibitors have long been used for the treatment of rheumatoid arthritis (RA), ankylosing spondylitis (AS), as well as other inflammatory conditions." (PMID 38256582, 2024). "Work in a rheumatoid arthritis model showed that ephrin B1 increased tumor necrosis factor alpha (TNFα) and interleukin-6 (IL-6) actions in lymphocytes." (PMID 38501146, 2024). "In the development of rheumatoid arthritis (RA), TNF-α, IL-1, IL-6, IL-2 and many other inflammatory factors mediate the inflammatory response." (PMID 38629066, 2024). "Tanshinones isolated from Danshen were able to ameliorate peroxidative damage, adjust the level of serum superoxide dismutase (SOD) and malonaldehyde (MDA), and inhibit the secretion of IL-6 and TNF-α, thus attenuating rheumatoid arthritis (RA)." (PMID 38542838, 2024). "The potential core targets for Mugua treatment of rheumatoid arthritis are IL-6, TNF, IL-1β, and IL-10." (PMID 39705460, 2024). "TNF is heavily involved in inflammatory pathways and immune regulation, which are critical in diseases such as rheumatoid arthritis, ulcerative colitis, diabetes mellitus, and myocardial infarction." (PMID 39337647, 2024). "For example, anti-TNFα agents such as etanercept have found promise in inflammatory conditions such as rheumatoid arthritis." (PMID 38585987, 2024).
rheumatoid arthritis (continued). "Our objective was to explore their association with the development, progression, and response to TNF inhibitor treatment in patients diagnosed with rheumatoid arthritis and ankylosing spondylitis." (PMID 38714580, 2024). "A handful of TNF-specific monoclonal antibodies are currently approved for treating rheumatoid arthritis and other diseases such as juvenile idiopathic arthritis, psoriatic arthritis, ankylosing spondylitis, ulcerative colitis, Crohn’s disease, and psoriasis." (PMID 39584990, 2024). "TNF-α activity impairments have been reported in various inflammatory or immune-mediated diseases, such as rheumatoid arthritis, inflammatory bowel disease, and cancer." (PMID 38397895, 2024). "The patient received adalimumab, a tumor necrosis factor inhibitor antibody, as part of his treatment for rheumatoid arthritis." (PMID 38846411, 2024). "Clinical trials have shown that quercetin supplementation significantly improved clinical symptoms and plasma TNF-α levels in patients with rheumatoid arthritis." (PMID 39139212, 2024). "In patients with psoriasis and rheumatoid arthritis, previous studies have suggested that it increases pro-inflammatory cytokines, mainly IL-6 and tumor necrosis factor-alpha (TNF-a)." (PMID 39007024, 2024). "Integrated RNA-seq and ATAC-seq of rheumatoid arthritis fibroblast-like synoviocytes from different joint locations after culture in medium or TNF indicates joint-specific phenotypes contribute to the distribution and severity of joint inflammation." (PMID 38781031, 2024). "DN memory B cells have been shown to be significantly reduced in rheumatoid arthritis patients treated with TNF inhibitors and tocilizumab, as well as in lupus patients with nephritis undergoing immunosuppressive therapy." (PMID 39768154, 2024). "TAK1 is known to play a critical role in mediating TNF signal transduction and downstream NF-κB activation, helping to sustain pro-inflammatory signaling in diseases including rheumatoid arthritis, irritable bowel disease and lupus." (PMID 38632238, 2024). "Neutralization of TNF is a highly effective therapeutic intervention in many inflammatory diseases, such as rheumatoid arthritis, ankylosing spondylitis, psoriasis, Crohn's disease, and endotoxin‐induced septic shock." (PMID 38459711, 2024). "Due to exacerbated inflammation, anti–TNF-α biologics are approved for autoimmune diseases such as rheumatoid arthritis, psoriasis, Crohn’s disease, and ulcerative colitis." (PMID 38713531, 2024). "Adalimumab is a therapeutic monoclonal antibody developed to target human TNF an important mediator of immune-mediated inflammatory diseases such as rheumatoid arthritis, amongst others." (PMID 38926254, 2024). "The pathways included in the plot are labelled as rheumatoid arthritis, Lipid and atherosclerosis, IL‐17 signalling pathway, TNF signalling pathway and other pathways are related to rheumatology and immunology." (PMID 39087591, 2024). "MSCs are remarkably effective in controlling the inflammatory cytokines that are elevated in rheumatoid arthritis, including tumor necrosis factor-alpha (TNFα), which is a cytokine that plays a significant role in pathogenesis." (PMID 38715140, 2024). "TNF-α is widely distributed in all actively inflamed tissues, including the synovial fluid of individuals with rheumatoid arthritis or plaquegiria, as well as the eye in cases of acute uveitis." (PMID 39407875, 2024). "An increase in the serum levels of TNF-α was also observed in adult patients with ankylosing spondylitis (AS) and rheumatoid arthritis (RA) treated with etanercept despite clinical improvement." (PMID 38775868, 2024). "Tumor necrosis factor-alpha (TNF-α) is a proinflammatory cytokine that plays an important role in the pathogenesis of rheumatoid arthritis (RA), ankylosing spondylitis (AS), and many other inflammatory diseases." (PMID 39734351, 2024).
rheumatoid arthritis (continued). "Given its central role in the inflammatory response and immune regulation, researchers have developed numerous drugs targeting TNF-α for conditions such as rheumatoid arthritis and Crohn’s disease." (PMID 38571956, 2024). "Improvements in systemic insulin sensitivity in humans treated with anti-TNF-α therapies for inflammatory diseases like rheumatoid arthritis also suggest a potential therapeutic role for TNF-α." (PMID 38807790, 2024). "Infliximab is a monoclonal TNF-α inhibitor that is used in the treatment of several TNF-α-mediated disorders such as rheumatoid arthritis, psoriasis, ulcerative colitis, and Crohn’s disease." (PMID 38776022, 2024). "Adalimumab (brand names Humira, Amgevita, Hyrimoz, Idacio, Imraldi, and Yuflyma), which is used to treat conditions such as Crohn's disease and rheumatoid arthritis, targets and inhibits tumor necrosis factor-alpha (TNF-α)." (PMID 38745971, 2024). "TNF-α plays a critical role in immune-inflammatory diseases like rheumatoid arthritis, and symptom relief in patients can be effectively achieved by inhibiting TNF-α." (PMID 38800832, 2024). "According to a previous report in patients with rheumatoid arthritis, the presence of anti-BSA antibody severely interferes with the anti-tumor necrosis factor antibody test results only in enzyme-linked immunoassays, which contain BSA as a blocking agent." (PMID 39247764, 2024). "Regarding the KEGG pathway, significant enrichment pathways were TNF, IL-17 signaling pathway, rheumatoid arthritis, NF-κb, and B-cell receptor signaling pathway." (PMID 39739658, 2024). "For example, siRNA therapies targeting tumor necrosis factor-alpha (TNF-α), a key player in rheumatoid arthritis, have shown potential in preclinical studies." (PMID 39598489, 2024). "In synovial fibroblasts of patients with rheumatoid arthritis Tumor Necrosis Factor (TNF) drives the expression of Jagged-2, Notch-1, and Notch-4, along with a hallmark of Notch activation, the Notch intracellular domain (NICD) nuclear translocation." (PMID 38314334, 2024). "Generally, a high level of tumor necrosis factor (TNF) can be observed in inflammatory disorders, so the over-expression of the TNF-α induced by p38α can be considered as an indicator for progressive autoimmune diseases as rheumatoid arthritis." (PMID 38611731, 2024). "Rheumatoid arthritis is characterized by systemic inflammation (high levels of proinflammatory cytokines–TNF, IL-1, IL-6, matrix metalloproteinases-MMP, circulating autoantibodies) that disrupt bone metabolism." (PMID 38672734, 2024). "Tumor necrosis factor alpha (TNF-α) is a key proinflammatory cytokine that plays a central role in the pathogenesis of various autoimmune conditions ranging from rheumatoid arthritis to inflammatory bowel disorders and beyond." (PMID 39712842, 2024). "Tumor necrosis factor (TNF) inhibitor (TNFi) therapy, commonly used to treat autoimmune conditions, such as ankylosing spondylitis (AS), rheumatoid arthritis, and psoriatic arthritis, has been associated with the development of drug-induced lupus (DIL)." (PMID 39606520, 2024). "Another study in patients with rheumatoid arthritis receiving the fully humanized anti-TNF monoclonal antibody adalimumab indicated beneficial effects of therapy on periodontal parameters." (PMID 39253090, 2024). "Due to its central role in inflammation and cell death, it has been a target for therapeutic interventions in diseases like rheumatoid arthritis and inflammatory bowel disease, where TNF inhibitors are used to reduce inflammation and tissue damage." (PMID 39660881, 2024). "Recently, anti-proinflammatory cytokine therapies against interleukin (IL)-6, tumor necrosis factor (TNF)-α, and IL-1 were introduced in inflammatory disease therapy, especially for rheumatoid arthritis." (PMID 38542934, 2024).
rheumatoid arthritis (continued). "Activating tumor necrosis factor receptor 1 (TNFR1) with tumor necrosis factor alpha (TNFα) is one of the key pathological mechanisms resulting in the exacerbation of rheumatoid arthritis (RA) immune response." (PMID 39519786, 2024). "In Group B vs Group C, differentially enriched pathways include the IL-17 signaling pathway, Prostate cancer, TNF signaling pathway, Rheumatoid arthritis, and Transcriptional misregulation in cancer." (PMID 38352714, 2024). "As TNF-α is not only involved in the development of inflammatory diseases but also autoimmune diseases, TNF-α inhibitors have been developed and are now used to treat autoimmune diseases such as rheumatoid arthritis (RA)." (PMID 38999258, 2024). "In rheumatoid arthritis (RA), fibroblasts activated by tumor necrosis factor (TNF) produce high levels of chemokines such as IL-6, CXCL12, and CCL2, which enhance the recruitment and attraction of monocytes." (PMID 39290699, 2024). "In patients with rheumatoid arthritis, TNF blockade biologically reduces not only TNF but also other pro-inflammatory cytokines that are important in the hyper-inflammation of COVID-19." (PMID 39118801, 2024). "Sulfasalazine is commonly used to treat rheumatoid arthritis and reduces TNF and prostaglandin synthesis, providing therapeutic benefits." (PMID 39432502, 2024). "Fortunately, some neutralizing antibodies against IL-1α and TNF-α are already in practical use for treating cancers, rheumatoid arthritis, and other chronic local inflammatory diseases." (PMID 38383466, 2024). "While anti-TNF therapies have long been a mainstay in the treatment of auto-immune diseases such as rheumatoid arthritis, they are increasingly being investigated in cancers." (PMID 39543125, 2024). "At present, one of the most promising target of therapeutic intervention is TNFα, since the observation that rheumatoid arthritis patients treated with the TNFα inhibitor Etanercept have lower risk to develop AD." (PMID 39835288, 2024). "Corresponding to the RT-qPCR results, the ASFV + ALO group also enriched inflammation-related signaling pathways, such as the IL-17 signaling pathway, TNF signaling pathway, NF-κB signaling pathway, and rheumatoid arthritis (inflammation)." (PMID 39201769, 2024). "In fact, anti-TNF-α therapy improves microvascular endothelial dysfunction in rheumatoid arthritis patients with atherosclerosis." (PMID 39769009, 2024). "In experimental models, aurothiomalate has been shown to effectively suppress TNF-α production in synovial fibroblasts derived from rheumatoid arthritis patients." (PMID 38344607, 2024). "CZP is a PEGylated Fc free TNF-inhibitor used in the treatment of rheumatoid arthritis and other chronic inflammatory diseases." (PMID 37943398, 2024). "We have previously demonstrated that TAK1 inhibition by LLZ reduced joint inflammation and bone destruction by inhibiting NLRP3 inflammasome and TNF-α expression in collagen-induced arthritis, a mouse model of rheumatoid arthritis." (PMID 38891908, 2024). "A rheumatoid Arthritis C57BL/6 SCID mouse model carrying a human TNF transgene when treated with intermittent doses of DAPT showed improved bone regeneration." (PMID 39401071, 2024). "KEGG results showed that the first five major pathways of enrichment were Cytokine−cytokine receptor interaction、Human T−cell leukemia virus 1 infection、TNF signaling pathway、Rheumatoid arthritis、Viral protein interaction with cytokine and cytokine receptor." (PMID 38451963, 2024). "It is known to play a role in rheumatoid arthritis because it can induce TNF α, a major cytokine in Rheumatoid Arthritis." (PMID 39095691, 2024). "Among these treatments, anti-tumor necrosis factor alpha (TNFa) is commonly used in the treatment of rheumatoid arthritis and other forms of arthritis." (PMID 39717315, 2024).
rheumatoid arthritis (continued). "The pro-inflammatory cytokines tumor necrosis factor (TNF), interleukin (IL)-6, IL-1β, IL-17, and others generate and maintain inflammation in rheumatoid arthritis and related diseases." (PMID 39596013, 2024). "TNFα-neutralizing therapies are effective in rheumatoid arthritis joints as well as many other chronic inflammatory diseases." (PMID 38404573, 2024). "A 75-year-old woman on tumor necrosis factor inhibitors for rheumatoid arthritis presented with hematemesis and a gastric biopsy revealed diffuse large B-cell lymphoma with possible bulky left liver tumor involvement." (PMID 38646371, 2024). "Among these markers, TNF-α plays a pivotal role in the pathogenesis of various diseases, particularly chronic inflammation that links rheumatoid arthritis, atherosclerosis, and impaired insulin sensitivity." (PMID 38397603, 2024). "Ozoralizumab, a trivalent anti-tumor necrosis factor alpha (TNFα) humanized single-domain antibody, is approved for the treatment of rheumatoid arthritis." (PMID 38732011, 2024). "The dif-lncRNA-targeted genes were predominantly involved in viral protein interactions with cytokine and cytokine receptors, rheumatoid arthritis, the cytosolic DNA-sensing pathway, influenza A, and the TNF signalling pathway." (PMID 39334220, 2024). "In patients with rheumatoid arthritis receiving TNF blockers, lower periodontal indices including plaque index, gingival index, probing depth, clinical attachment loss, and bleeding on probing were found." (PMID 39253090, 2024). "We identify exosomal TNF-α as a key factor to induce neural hyperexcitability, and we propose the use of the FDA-approved drug infliximab, an inhibitor of TNF-α commonly used to treat rheumatoid arthritis, as a novel agent to treat BTRE." (PMID 39088270, 2024). "Background and Objectives: Anti-tumor necrosis factor-alpha (TNF-α) agents are effective in treating rheumatoid arthritis (RA) but may entail a risk of lymphoma due to TNF-α’s role in immune surveillance." (PMID 39064585, 2024). "TNF inhibitors, a class of drugs used to treat various inflammatory diseases, were investigated initially for treating rheumatoid arthritis." (PMID 38335182, 2024). "We have previously demonstrated that TAK1 inhibition by LL-Z1640-2 (LLZ) reduced joint inflammation and bone destruction by inhibiting NLRP3 inflammasome and TNF-α expression in collagen-induced arthritis, a mouse model of rheumatoid arthritis." (PMID 38891908, 2024). "We selected 50 pg/mL TNFα for the continuous inflammatory stimulation based on the lower limit of reported TNFα concentrations in the synovial fluid of patients with rheumatoid arthritis." (PMID 38443999, 2024). "To further validate the role of LOXL1 in rheumatoid arthritis, we simulated the inflammatory environment of rheumatoid arthritis in vitro by stimulating SW982 cells with TNF-α." (PMID 38217541, 2024). "In 2002, the FDA approved Humira (adalimumab), the first human antibody derived from phage display, for the treatment of rheumatoid arthritis by targeting TNF-α." (PMID 39584990, 2024). "KEGG pathway analysis highlighted a strong involvement of these DEGs in the interleukin 17 (IL-17) signaling pathway, the tumor necrosis factor (TNF) signaling pathway, the transcriptional misregulation in cancer, the rheumatoid arthritis and other pathways." (PMID 39600608, 2024). "SOF also significantly diminished the serum level of TNF-α and IL-1β in rheumatoid arthritis, and cisplatin-induced nephrotoxicity." (PMID 38874805, 2024). "TNF-α is released during the early stages of both acute and chronic inflammatory conditions, such as septic shock, rheumatoid arthritis, and allergic reactions." (PMID 39355840, 2024). "Adalimumab is an antibody targeting tumor necrosis factor-α (TNF-α) which has been used effectively in passive immunotherapy for rheumatoid arthritis." (PMID 38715084, 2024).